ZDHHC13 (zDHHC palmitoyltransferase 13)
Diseases named in the same sentence as ZDHHC13 in open-access papers (continued):
Sharing a sentence is not in itself a finding about the gene and the disease.
Osteopenia (1 paper, 2014). Osteopenia is a term to define bone density that is not normal but also not as low as osteoporosis. "Previous studies reported a phenotype for MT1-MMP (membrane type 1- matrix metalloproteinase, also known as MMP14)-deficient mice that was remarkably similar to that of the Zdhhc13 mutant, namely, impaired endochondral ossification, defective angiogenesis, and osteopenia." (PMID 24637783, 2014).
skin cancer (1 paper, 2024). "A protective role for zDHHC13 in skin cancer was uncovered by a spontaneous mutation in the zDHHC13 gene (Zdhhc13luc), leading to a premature stop codon and the production of a truncated zDHHC13 protein with loss‐of‐function." (PMID 39429488, 2024).
tumor (4 papers, 2019 to 2025). "Macrophage depletion abolished the tumor-suppressive effect of ZDHHC13, indicating that macrophages are essential mediators of this response." (PMID 41321310, 2025). "In contrast, in immunocompetent C57BL/6J mice, ZDHHC13 overexpression significantly suppressed both subcutaneous tumor growth and pulmonary metastatic colonization following tail vein injection." (PMID 41321310, 2025). "To confirm ZDHHC13’s influence on immune cell infiltration, we analyzed B16 tumor-infiltrating immune cells using flow cytometry." (PMID 41321310, 2025). "To unify our mechanistic insights, we developed an integrated model that encompasses both the tumor-intrinsic and immune-regulatory functions of ZDHHC13." (PMID 41321310, 2025). "Notably, mice with transgenic expression of ZDHHC13 exhibited significantly improved survival rates and delayed tumor growth." (PMID 41321310, 2025). "In this model, ZDHHC13 overexpression significantly suppressed tumor growth, supporting the hypothesis that ZDHHC13’s antitumor activity is mediated through modulation of protumor macrophages." (PMID 41321310, 2025). "Given that the tumor immune microenvironment influences many aspects of cancer behavior, we cannot exclude the possibility that ZDHHC13 affects multiple stages of the metastatic cascade, including tumor cell delamination, invasion, survival, and subsequent proliferation at the metastatic site." (PMID 41321310, 2025). "ZDHHC17 and ZDHHC20 may act as oncoproteins 43, 44, but ZDHHC2 and ZDHHC13 can act as tumor suppressors 45-47." (PMID 32863941, 2020). "Consequently, ZDHHC13 activity suppresses tumor growth and metastasis in immunocompetent mice." (PMID 41321310, 2025). "Based on these observations, we hypothesize that ZDHHC13 may impact SM and LPC metabolism pathways to influence tumor immune responses." (PMID 41321310, 2025).
metabolic disease (1 paper, 2017). A congenital disorder (due to inherited enzyme abnormality) or acquired (due to failure of a metabolically important organ) disorder resulting from an abnormal metabolic process. "A systematic network of protein–protein interactions showed that these candidate ZDHHC13 substrates are associated with energy production, metabolic diseases, and the maintenance of cellular function." (PMID 28526873, 2017). "Our MS-based systematic analysis demonstrated that 111 of 307 candidate ZDHHC13 substrates were associated with metabolic disease, including mitochondrial dysfunction." (PMID 28526873, 2017).
ZDHHC13 also shares sentences with these, for which no sentence is quoted: cancer (2 papers); schizophrenia (2); Alzheimer disease (1); anxiety disorder (1); Ataxia (1); bipolar disorder (1); Cachexia (1); Failure to thrive (1); Kyphosis (1); liver cancer (1); lung carcinoma (1); mental disorder (1); neurodegenerative disease (1); neurological disorders (1); thyroid gland disease (1); X-linked intellectual disability (1).